MUTYH (mutY DNA glycosylase)
Diseases named in the same sentence as MUTYH in open-access papers (continued):
Sharing a sentence is not in itself a finding about the gene and the disease.
angioma (1 paper, 2021). "The patient (II-1) with the (c.536A>G; p.(Tyr179Cys)) variant in MUTYH had angioma of the upper gingival arch at 36 years and monolateral infiltrating BC at 52 years." (PMID 34026625, 2021).
Anxiety (1 paper, 2022). Intense feelings of nervousness, tension, or panic often arise in response to interpersonal stresses. "In this context, it has been shown that mice lacking the DNA glycosylases OGG1 and MUTYH — upstream enzymes involved in BER responsible for removing damaged bases — show a decrease in anxiety and impaired learning ability, potentially due to altered hippocampal gene expression." (PMID 35907861, 2022).
Ataxia (1 paper, 2024). Ataxia refers to impaired coordination of voluntary muscle movement. "In turn, 5–9% of Arabian horses are burdened by the occurrence of cerebellar abiotrophy (CA), a neurodegenerative, autosomal recessive disease caused by a mutation of mutY DNA glycosylase (MUTYH) gene that results in the loss of Purkinje neurons and causes ataxia in foals." (PMID 38263320, 2024).
B-cell neoplasm (1 paper, 2021). A group of heterogeneous lymphoid tumors generally expressing one or more B-cell antigens or representing malignant transformations of B-lymphocytes. "Out of 15 patients, 4 (26.6%) with subsequent mature B-cell neoplasms had germline pathogenic mutations in cancer susceptibility genes; MUTYH and WRN in 2 subsequent DLBCL patients and RAD50 and LZTR1 in 2 subsequent PCM patients." (PMID 34093829, 2021).
basal cell carcinoma (1 paper, 2024). A carcinoma involving the basal cells. "This case describes a patient with recurrent basal cell carcinomas (BCC) and subsequent genetic testing that revealed a pathogenic monoallelic mutation of the MUTYH gene, as well as the interventions that were subsequently performed." (PMID 38586659, 2024).
cardia (1 paper, 2023).
clear cell renal cell carcinoma (1 paper, 2020). "Ten pathogenic or likely pathogenic (P/LP) variants were identified in 11 sporadic clear cell renal cell carcinoma patients (10.38%), including rarely reported ATM (n=1), MUTYH (n=1), NBN (n=1), RAD51D (n=1), and BRCA2 (n=1)." (PMID 33062672, 2020).
CMMRD syndrome (1 paper, 2022). "When evaluating patients with early onset of multiple adenomatous polyps in the absence of proven APC germline mutations, the differential diagnosis needs to include attenuated-FAP, mutY homologue (MUTYH)-associated polyposis and constitutional mismatch repair deficiency (CMMRD) syndrome." (PMID 36002671, 2022).
CNS embryonal tumor (1 paper, 2022). "A biopsy was undertaken (resection was deemed high risk) and demonstrated a CNS embryonal tumor (WHO grade 4) with somatic mutations in retinoblastoma 1 (RB1) and mutY DNA glycosylase (MUTYH)." (PMID 35677741, 2022).
Cognitive impairment (1 paper, 2021). Abnormal cognition is characterized by deficits in thinking, reasoning, or remembering. "We also clarified that MUTYH deficiency in AppNL-G-F/NL-G-F knock-in AD model mice improved behavioral and cognitive impairments and significantly decreased microgliosis." (PMID 34970419, 2021). "Our results strongly suggest that MUTYH actively contributes to AD pathogenesis by activating microglia and impairing neurogenesis in the hippocampus, thus resulting in the mild cognitive impairment seen in AppNL-G-F/NL-G-F mice." (PMID 34970419, 2021).
colitis (1 paper, 2020). Inflammation of the colon. "The lack of a colitis response in Mutyh-/- mice was attributed to a role for MUTYH in mounting an inflammatory response." (PMID 31935236, 2020).
depression (1 paper, 2025). "Furthermore, a previous study demonstrated that single nucleotide polymorphisms (SNPs) in OGG1 and MUTYH are associated with depression, further emphasizing a significant role of DNA glycosylases in affect regulation and mental health." (PMID 40779073, 2025).
Gitelman syndrome (1 paper, 2020). Gitelman syndrome (GS), also referred to as familial hypokalemia-hypomagnesemia, is characterized by hypokalemic metabolic alkalosis in combination with significant hypomagnesemia and low urinary calcium excretion. "In this paper, we hypothesize and provide evidence that chronic magnesium deficiency from Gitelman syndrome may have potentiated oxidative DNA damage and enabled the phenotypic manifestation of monoallelic MUTYH mutation in this patient." (PMID 33024574, 2020). "In summary, this report highlights the potential pathobiological relevance of germline monoallelic MUTYH mutations in the presence of cooperative non-genetic mechanisms, in this case possibly chronic magnesium deficiency from Gitelman syndrome." (PMID 33024574, 2020). "We postulate that monoallelic MUTYH mutations may manifest in the presence of cooperative non-genetic mechanisms, in this case possibly magnesium deficiency from Gitelman syndrome." (PMID 33024574, 2020).
hereditary cancer-predisposing syndrome (1 paper, 2023). "MUTYH variants can be deleterious—damaging its function—and 172 germline MUTYH variants have been determined as pathogenic, causing MAP and hereditary cancer-predisposing syndrome." (PMID 36979362, 2023).
hyperplastic (1 paper, 2017). "Synovial hyperplasia in RA is similar to a hyperplastic tumor, together with the fact that increased oxidative DNA damage and oxidative stress have been demonstrated in RA patients, we believed that MUTYH might have a role to play in RA pathology." (PMID 28173856, 2017).
Insulin resistance (1 paper, 2021). Increased resistance towards insulin, that is, diminished effectiveness of insulin in reducing blood glucose levels. "The AD brain exhibits insulin resistance, and T2DM is a major risk factor for AD; therefore, insulin secretagogues which can induce MUTYH degradation are promising therapeutic agents for the prevention of the AD pathogenesis." (PMID 34970419, 2021).
membranous nephropathy (1 paper, 2020). "In these studies, the association of the IL-6, NPHS1 (nephrin), TLR-4, TLR-9, STAT4 (signal transducer and activator of transcription) and MYH (mutY DNA glycosylase), genes with susceptibility to primary membranous nephropathy in Taiwan was established." (PMID 32933213, 2020).
neuroendocrine tumors (1 paper, 2021). "A recent whole-genome sequencing study of pancreas neuroendocrine tumors suggested that sporadic neuroendocrine tumors contain an elevated proportion of germline mutations in the DNA repair genes MUTYH, CHEK2, and BRCA226." (PMID 34031376, 2021).
neuroepithelial tumors (1 paper, 2025). "High-grade neuroepithelial tumors with germline mutations in MUTYH predominantly affected children and young adults, with no sex predominance." (PMID 40469416, 2025).
papillary breast cancer (1 paper, 2014). "To explore whether biallelic MUTYH mutations are a frequent cause underlying the development of papillary carcinomas of the breast, we analyzed the prevalence of germline MUTYH mutations in an unselected patient group with papillary breast cancer." (PMID 25937855, 2014). "No germline mutations were identified, indicating that biallelic MUTYH mutations are not a frequent underlying cause for the development of papillary carcinomas of the breast." (PMID 25937855, 2014).
papillary carcinomas of the (1 paper, 2014). "Our data do not confirm that biallelic germline MUTYH mutations are a frequent underlying cause of papillary carcinomas of the breast." (PMID 25937855, 2014). "In our study we could not identify the association between MUTYH mutations and papillary carcinomas of the breast in an unselected group of patients with papillary carcinomas." (PMID 25937855, 2014).
prostate tumours (1 paper, 2024). "Furthermore, reduced gene and protein expression of MUTYH in prostate tumours has been associated with an increase in total somatic mutations, which may result from impaired DDR capacity." (PMID 39001544, 2024).
renal cell cancer (1 paper, 2024). "The cited authors report that VHL, BAP1, FH, and MET are specific genes that increase the risk of developing renal cell cancer, whereas CHEK2, MUTYH, APC, and STK1 are not typically associated with the development of renal tumours." (PMID 39336594, 2024).
renal fibrosis (1 paper, 2015). A final common manifestation of a wide variety of chronic kidney diseases characterized by glomerulosclerosis and tubulointerstitial fibrosis. "These inconsistencies implied that mechanisms in addition to the oxidative DNA damage underlying renal fibrosis were involved in MUTYH regulation." (PMID 26576226, 2015). "Increased MUTYH expression was associated with the severity of renal fibrosis." (PMID 26576226, 2015). "This implied that MUTYH might be implicated in the pathogenesis of renal fibrosis." (PMID 26576226, 2015). "The in vivo and in vitro responses of MUTYH (mitochondrial and/or nuclear forms) in renal fibrosis were investigated in the present study." (PMID 26576226, 2015). "To explore the response of MUTYH in renal fibrosis in vitro, we analyzed HK-2 cells treated by H2O2 and TGF-β1." (PMID 26576226, 2015). "Taken together, our results demonstrated the regulation of MUTYH in tubule cells in renal fibrosis." (PMID 26576226, 2015). "The present study is fundamental for further studies, and our ongoing studies showed that MUTYH deficiency protects mice from renal fibrosis (data not shown)." (PMID 26576226, 2015). "Although the results in the present study could not demonstrate the role of MUTYH on renal fibrosis, the significance of this study is by the first time to illustrate the association between MUTYH regulation and renal obstruction." (PMID 26576226, 2015).
cancer (197 papers, 2004 to 2026). A tumor composed of atypical neoplastic, often pleomorphic cells that invade other tissues. "The association of monoallelic MUTYH variants with cancer risk, clinical impact, and management remains controversial." (PMID 41347765, 2026). "Increased risks of CRC and other cancers have been reported in germline MUTYH heterozygotes (mono-allelic mutation carriers, frequency 2-3%), but the existence of these associations and underlying mechanism have remained controversial." (PMID 42092060, 2026). "We excluded probands with biallelic MUTYH mutations or co‐occurring PVs in other cancer susceptibility genes." (PMID 41001951, 2025). "They compared the prevalence of pathogenic monoallelic MUTYH variants between a large cancer cohort (from The Cancer Genome Atlas, TCGA) and an equally large cohort of healthy individuals (from Genome Aggregation Database, gnomAD)." (PMID 41001951, 2025). "Our sample size is not large enough to draw definitive conclusions; however, these findings provide supportive evidence for a potential role of monoallelic MUTYH in cancer predisposition." (PMID 41001951, 2025). "Recent findings have led to the proposal of the term MUTYH‐associated tumor syndrome (MATS) to more accurately reflect the broad cancer spectrum observed in carriers of germline MUTYH mutations, beyond the classical colorectal phenotype of MAP." (PMID 41001951, 2025). "Several pan‐cancer studies have demonstrated MUTYH inactivation or loss of heterozygosity across various tumor types, and reduced MUTYH expression has been reported in breast and gynecologic tumors from germline variant carriers." (PMID 41001951, 2025). "We found a double mutation (DM) in 6 patients, with one carrying a DM in MUTYH and the other 5 harboring mutations in MUTYH and other cancer susceptibility genes (CHEK2, BRIP1, MLH1, and BRCA1)." (PMID 41001951, 2025). "A similar outcome was also observed for other MUTYH pathogenetic variants in the same different cancer type control cohorts." (PMID 38790183, 2024). "A relative of MPT23, MPT23.2 (currently cancer-free), showed pathogenic CNVs of MUTYH, therefore requiring clinical monitoring for CRC." (PMID 39408606, 2024). "Our data suggest that the germline mutator effect of MUTYH predominantly operates in a recessive manner, paralleling its role in cancer predisposition." (PMID 39403956, 2024). "MAP follows a recessive inheritance pattern, affecting individuals who have inherited 2 subfunctional copies of the MUTYH gene, causing intestinal adenomatous polyposis as well as an elevated risk for early-onset colorectal and duodenal malignancies." (PMID 39403956, 2024). "Due to the essential role of MUTYH gene in DNA repair, it has been implicated in many other cancers." (PMID 37656691, 2023). "More recently, the use of enlarged genomic testing in cancer patients has shown that MUTYH monoallelic variants are identified in BRCA1/2-negative BC patients, even if with a frequency similar to that of the expected carrier frequency." (PMID 36035419, 2022). "Although MUTYH is considered an AR predisposition gene, several studies also suggest a modestly increased cancer risk for heterozygous mutation carriers." (PMID 35739278, 2022). "Pathogenic/likely pathogenic variants were identified in 35% of patients in known cancer genes such as MUTYH and ATM." (PMID 36077770, 2022). "In total, 17 (94%) of the variants were private to a single person and were mostly related to cancer predisposition genes such as MUTYH, MSH6, BRCA2, and PALB2." (PMID 35562925, 2022). "SBS36 has previously been found in cancers with germline or somatic MUTYH mutations and is also characterised by C > A mutations, albeit with a different profile of preferred trinucleotide contexts from SBS1830–33." (PMID 35803914, 2022). "All patients were heterozygous for all variants, including those harboring variants in MUTYH for which the monoallelic variant has an unclear risk of cancer." (PMID 34830767, 2021).
cancer (continued). "The contribution of the genetic variants, other than MSH6 and MUTYH, to cancer risk cannot be completely excluded." (PMID 32615015, 2020). "Here, we demonstrate the coinheritance of MSH6 and MUTYH variants consistent with the cosegregation with cancer, further supporting a role for digenic inheritance in CRC predisposition." (PMID 32615015, 2020). "Digenic inheritance of monoallelic MSH6 and MUTYH variants has been suggested to predispose to Lynch syndrome‐associated cancers; however, cosegregation of both variants within CRC families has not yet been demonstrated." (PMID 32615015, 2020). "Digenic inheritance of monoallelic MSH6 variants of uncertain significance and MUTYH variants has been suggested to predispose to Lynch syndrome‐associated cancers; however, cosegregation with disease in the familial setting has not yet been established." (PMID 32615015, 2020). "The 12 missense variants were benign as judged by the ClinVar significance, with one exception, MUTYH, which is a recessive cancer predisposition gene." (PMID 32992489, 2020). "For example, the deactivation of MUTYH gene in cancer patients is associated with a specific mutational signature." (PMID 32471470, 2020). "In regard to cancer, in patient 52, we discovered the presence of variants (c.1437_1439delGGA, p.Glu480del, and rs587778541) in the MUTYH gene and (c.470T > C, p.Ile157Thr, and rs1787996) in the CHEK2 gene." (PMID 32695137, 2020). "Thirteen of them were variants predicted as pathogenic by in silico tools, identified in well-known CRC predisposing genes such as APC and MUTYH, as well as variants in newly emerging cancer predisposing genes such as MSH3 and FAN1." (PMID 32635641, 2020). "MAP is a hereditary colorectal cancer syndrome that is caused by adenoma and cancers with a cumulative 8-Oxo guanine (8-OxoG), which causes mutation in the mutY homolog E. coli (MUTYH) gene." (PMID 31724937, 2019). "The frequency of mono-allelic MUTYH mutations in our patients with different primary cancers but who were all clinically suspected to have hereditary cancer predisposition is similar to what has been reported in the literature." (PMID 30093976, 2018). "Nevertheless, the risk that monoallelic MUTYH mutations confer is uncertain, so it is unlikely that they are the only cause of cancer in the corresponding families." (PMID 30256826, 2018). "The association of MUTYH variants with malignancies other than colon cancer is less robust, especially when establishing cancer risks in heterozygous MUTYH individuals." (PMID 30564557, 2018). "From variant analysis of 46 cancer susceptibility genes, we identified 7 pathogenic and likely pathogenic germline variants in 7 genes in 7 (8%) of the 87 patients, namely, MUTYH, RET, TSC2, BRCA1, BRCA2, ERCC2 and HRAS." (PMID 29684080, 2018). "Overall, we observed that the majority of MBC patients with pathogenic MUTYH variants have first-degree family history of cancers." (PMID 30564557, 2018). "To further investigate the role of MUTYH in MBC, we evaluated the risk of MBC associated with selected MUTYH variants previously proposed to be associated with increased cancer risk, including BC risk, by performing a case-control study." (PMID 30564557, 2018). "MUTYH was chosen as a candidate gene because MUTYH polymorphisms and mutations have been associated with various cancers and cancer-linked inflammatory responses." (PMID 28173856, 2017). "Gene polymorphism and mutations that lead to MUTYH inactivation have been associated with many cancers and cancer-associated inflammatory responses." (PMID 28173856, 2017).